BCL2 (BCL2 apoptosis regulator)
Diseases named in the same sentence as BCL2 in open-access papers (continued):
Sharing a sentence is not in itself a finding about the gene and the disease.
colorectal cancer (continued). "We surveyed the percentage of copy number alternations of BCL2, BCL2L1 and MCL1 among a majority of these tumor samples and found that colorectal cancer has the highest percentage of BCL2L1 gain/amplification among all cancer types." (PMID 26134786, 2015). "We used migration and invasion assays as well as three dimensional cell cultures to analyze colorectal cancer cell lines (HT29 and SW480) after siRNA mediated knockdown or overexpression of Mcl-1, Bcl-2 or Bcl-xL." (PMID 24098503, 2013). "In order to investigate the expression of the antiapoptotic Bcl-2 proteins Mcl-1, Bcl-2 and Bcl-xL in human CRC cell lines, we measured protein levels in four colorectal cancer cell lines." (PMID 24098503, 2013). "In colorectal cancer (CRC) cell lines, B7-H3 has been shown to enhance resistance to apoptosis through the upregulation of the JAK2/STAT3 signaling pathway, resulting in an increased expression of anti-apoptotic proteins such as Bcl-2 and Bcl-xL." (PMID 40214484, 2025). "In colorectal cancer (CRC), BCL2 is recognized as a direct target of miR140-3p." (PMID 38285101, 2024). "To identify the best BH3 mimetic strategy, we analyzed mRNA ratios of MCL1 and BCL-XL, based on a previous study that showed a low ratio of MCL1:BCL-XL, in colorectal cancer (CRC) correlated with synthetic lethality between ERK pathway inhibitors and pan BCL-2 inhibitors." (PMID 36672327, 2023). "Not surprisingly, given the heterogeneity of KRASMT colorectal cancer, levels of BCL-2 proteins were variable across the cell line panel." (PMID 36279564, 2023). "Some studies have suggested that BCL2 expression has no prognostic significance in colorectal cancer." (PMID 38067251, 2023). "Similarly, in HT-29 colorectal cancer cells, activation of the intrinsic apoptosis pathway was demonstrated via upregulation of BAX and downregulation of BCL2." (PMID 35563174, 2022). "In addition, roburic acid induced the apoptosis of colorectal cancer cells by promoting the cleavage of PARP, Caspase3, Caspase7, and Caspase9, as well as downregulating the levels of the antiapoptotic proteins Bcl-2, Bcl-xL, XIAP, Mcl-1, and Survivin." (PMID 35222445, 2022). "In colorectal cancer HCT-15 cells, TSAIII treatment was found to induce apoptosis, as demonstrated by the activation of caspase, induction of cleaved-caspase-3, caspase-8, and caspase-9, and decreased expression of Bcl-xL and Bcl-2." (PMID 36611961, 2022). "In the present study, we found that shikonin induced the cell apoptosis of colorectal cancer cells by activating the ER stress through the PERK/elF2α/ATF4/CHOP and IRE1α/JNK signaling pathways, up-regulating the anti-apoptotic protein Bcl-2 and increasing the expression of caspase-3/9." (PMID 34976186, 2022).
colorectal cancer (continued). "In this regard, malvidin upregulated p21 expression levels in human colorectal cancer and its combined use with blueberry induced cell death through Bax-mediated intrinsic pathway in SCC131 cells by inhibiting Bcl-2 with an increase in Bax expression and initiating cleavage of caspases." (PMID 34768743, 2021). "The results of this study confirmed that the expression of ERCC1 in HCT-116/L-OHP cells was abnormally increased, as were the expression of Bcl-2, GST-π, MRP, P-gp, and survivin, indicating that the resistance of colorectal cancer cells to L-OHP is mediated through ERCC1." (PMID 33014113, 2020). "Western blot analysis also showed increased Bax content and decreased Bcl-2 content in the 3-MA pre-treated HCT116 and SW620 cells, suggesting that autophagic inhibition by 3-MA treatment enhanced myricetin-induced apoptosis in colorectal cancer cells." (PMID 32631392, 2020). "Recently, overexpression of miR-625-3p in colorectal cancer cell lines had been shown to provide resistance to apoptosis via downregulating p38-MAPK which is involved in phosphorylation and activation of the pro-apoptotic bcl-2 gene." (PMID 28854245, 2017). "Taken together, Dishevelled1-3 contributed to multidrug resistance in colorectal cancer via activating Wnt/β-catenin signaling and inducing the expressions of P-gp, MRP2, BCRP, Survivin and Bcl-2, independently of β-catenin accumulation and nuclear translocation." (PMID 29383202, 2017). "Thus, we detected the expression of caspase 3, caspase 8, and BCL-2, when AK027294 expression was significantly knocked down in colorectal cancer cells." (PMID 26820130, 2016). "On the other hand, the role of Bcl-2 in development or progression of colorectal carcinoma and prognosis of the disease has not been fully elucidated." (PMID 25864810, 2015). "Based on this study we conclude that Mcl-1, Bcl-2 and Bcl-xL contribute to migration and invasion of colorectal cancer cells independent of their antiapoptotic effects." (PMID 24098503, 2013). "The data presented indicate a pivotal role of Mcl-1, Bcl-2 and Bcl-xL for migration and invasion of colorectal cancer cells independent of their known antiapoptotic effects." (PMID 24098503, 2013). "The aim of this study was to dissect a potential role of the antiapoptotic Bcl-2 proteins Mcl-1, Bcl-2 and Bcl-xL on migration and invasion of colorectal cancer cells independent of their cell death control function." (PMID 24098503, 2013). "The PI3K/AKT pathway plays a pivotal role in the onset and progression of colorectal cancer, influencing autophagy, apoptosis, and EMT-mediated cancer cell migration and invasion, accompanied by regulation of CCND1, mTOR, FOXO, HIF-1α, CASP, Bax, and Bcl-2 expression." (PMID 38384287, 2024). "Finally, Western blot and qPCR showed that treatment with berberine (40 μM), a natural isoquinoline alkaloid derived from Berberis genus plants, decreased the expression of Bcl2 protein but not mRNA in human colorectal cancer cell lines HT-29 and HCT-116." (PMID 36364387, 2022). "Induction of colorectal cancer in mice impaired weight gain and feed intake, liver function and structural characteristics of ileum, while the dietary administration of nanoliposome-encapsulated PRF regulated the expression of Caspase 3, Bax, Bcl2, iNOS and SOD genes in the tumor tissue." (PMID 36552412, 2022). "In conclusion, we have demonstrated that ivermectin may regulate the expression of crucial molecules Caspase-3, Bax, Bcl-2, PARP, and Cleaved-PARP in the apoptosis pathway by increasing ROS production and inhibiting the cell cycle in the S phase to inhibit colorectal cancer cells." (PMID 34483925, 2021). "Moreover, the delayed cell cycle of colorectal cancer cells was not influenced by over-expression of pro-survival Bcl-2 proteins." (PMID 32367199, 2020).
colorectal cancer (continued). "We sought to determine whether an extensively validated, deterministic apoptosis systems model, ‘DR_MOMP’, could be used as a stratification tool for the apoptosis sensitiser and BCL-2 antagonist, ABT-199 in patient-derived xenograft (PDX) models of colorectal cancer (CRC)." (PMID 33066609, 2020). "Therefore, Bcl-2 and its transcription factor, NF-κB, may suppress tumor proliferation via the activation of PPAR-α in colorectal carcinoma." (PMID 31354797, 2019). "The expression of NF-κB-dependent anti-apoptotic genes (XIAP, Bcl-xl, and Bcl-2) was also shown to be downregulated, suggesting that miR-15b-5p negatively regulates NF-κB1 and IKK-α, resulting in the suppression of NF-κB-dependent survival proteins in colorectal cancer." (PMID 28646148, 2017). "In this study, the relative level of mRNA expression of Bax and Bcl-2 genes was determined using RNA extraction, cDNA synthesis and RT-qPCR technique from 22 tumoral tissues and adjacent non-tumoral tissues from adenocarcinoma colorectal cancer." (PMID 25864810, 2015). "We reported that stabilization of Bcl-2 protein via phosphorylation of Bcl-2 at Serine 87 (pBcl-2-S87) by PXN-mediated ERK activation conferred 5-fluorouracil (5-FU) resistance and an unfavorable response to 5-FU-based chemotherapy in colorectal cancer patients." (PMID 25826088, 2015). "Also, salinomycin induces apoptosis in cisplatin-resistant human colorectal cancer cells (Cisp-resistant SW620 cells) by increasing the protein expression of caspases 3, caspase 8, caspase 9 and BAX, but decreasing the protein expression of Bcl-2." (PMID 25531367, 2014). "However, a direct contribution of antiapoptotic Bcl-2 proteins to migration and invasion of colorectal cancer has not been investigated so far." (PMID 24098503, 2013). "So far, there is no study addressing the role of Bcl-2 on the metastasis in colorectal cancer." (PMID 24098503, 2013). "Lack of statistically significant correlation between Bcl-2 immuno-histochemical expression and prognostic parameters like tumor grade and stage, suggests that Bcl-2 immunoexpression may not be a significant prognostic marker in colorectal carcinoma." (PMID 31754362, 2019). "We also established that the Bax/Bcl-2 ratio was lower in differentiated than in non-differentiated cells, confirming the same findings in normal and tumor tissue and suggesting that this ratio could be used as a prognostic or predictive marker for the fate of colorectal cancer cells upon treatment." (PMID 36613399, 2023). "In the study of a large cohort of colorectal cancers, BCL-XL, but not BCL2 or MCL-1, emerged as a highly active protein, and its transcript level was the highest among the anti-apoptotic BCL2 genes." (PMID 34202143, 2021). "While targeting BCLxL, but not BCL2 or MCL1, on its own had some impact, most (15/17) of the immortalized colorectal cancer cell lines studied were efficiently killed by the combined targeting of BCLxL and MCL1." (PMID 32913182, 2020). "The current study shows that—in the pancreatic and colorectal cancer cell lines Panc-1, PaTu 8988t, and SW 480—staurosporine does not influence BAX, but influences the anti-apoptotic factor Bcl2." (PMID 30686270, 2019). "In SW480 and HCT-116 colorectal cancer cells, the downregulation of the β-catenin pathway and increase in the mitochondrial membrane potential depolarization increased the BAX:Bcl-2 ratio and although there was no change in caspase, apoptosis was induced by AIF." (PMID 36142874, 2022). "Whether BCL2, or its close relatives such as BCLxL or MCL1, is critical for maintaining the survival of solid cancers, including colorectal cancers (CRCs), is not fully defined." (PMID 32913182, 2020).
colorectal cancer (continued). "Similarly, SW620 cells, another colorectal carcinoma line, responded to the inhibitor of BCL-XL but not BCL2 when combined with AT101." (PMID 32824203, 2020).
pancreatic cancer (275 papers, 1999 to 2025). "Bru was shown to reduce proliferation and cause apoptosis in PATU-8988 and PANC-1 pancreatic cancer cells by lowering Bcl-2 expression and enhancing Bax and cleaved Caspase-3 expression." (PMID 38397437, 2024). "Chios Mastiha also caused a reduction in the anti-apoptotic bcl-2 protein levels and increased the pro-apoptotic bax protein levels in human pancreatic carcinoma cell lines BxPC-3 and COLO357." (PMID 37048208, 2023). "RRM2 upregulates the apoptosis-associated factor Bcl-2 and reduces Cleaved Caspase-3 in pancreatic cancer." (PMID 35248107, 2022). "The strong effects of SAL in combination with CEL on pancreatic cancer cells were associated with decreases in NF-κB activity and Bcl-2 and pAkt levels." (PMID 32714082, 2020). "Ectopic expression of miR-34a, as tumor suppressive miR, caused downregulation of Bcl-2, Notch1, and Notch2 and also inhibition of cell proliferation and invasion, induction of apoptosis and cell cycle arrest in pancreatic cancer cells." (PMID 32489562, 2020). "Correlation analysis revealed that the expression of BNIP3 was negatively associated with Bcl-2 (r=-0.476, P=0.001) and positively associated with Bax in pancreatic cancer tissues (r=0.333, P=0.005)." (PMID 28968982, 2017). "During our study of the expression of a Bcl2 mRNA variant in our Ela-mycPT1 mouse pancreatic cancer cell line, we serendipitously obtained a chimeric cDNA that was a fusion between the Bcl2 and the Nek9 genes." (PMID 27148738, 2016). "Extensive resistance to chemotherapy-induced apoptosis is a complicating factor in treating pancreatic cancer and has been linked to cellular overexpression of Bcl-2 and other apoptosis inhibitors." (PMID 23349858, 2013). "The GSPs-induced apoptosis of pancreatic cancer cells was associated with a decrease in the levels of Bcl-2 and Bcl-xl and an increase in the levels of Bax and activated caspase-3." (PMID 22905202, 2012). "Western blot analysis of pancreatic cancer cell lines proved that the combination treatment affected the levels of BCL2, known to be associated with apoptosis and cancer metastasis, and in tissues from treated mice, a decrease in BCL2 and phospho-STAT3 (Y705) was found." (PMID 38397018, 2024). "In addition, when assessing the mechanisms underlying the promotion of apoptosis in pancreatic cancer, we found that TQ can affect the cell cycle and regulate Bax and Bcl-2." (PMID 36686732, 2022). "Genistein, which inactivated NF-kB and caused transcriptional inactivation of Bcl-XL and Bcl-2, could be combined with (−)-gossypol to inactivate the function of Bcl-XL and Bcl-2 and then enhanced the death of pancreatic cancer cells." (PMID 28232946, 2017). "In this study we found that emodin reversed the gemcitabine resistance effect in pancreatic cancer, the action might be associating with down-regulation of NF-κB expression, and lowering the expression of P-gp and Bcl-2, increasing Bax expression." (PMID 22159556, 2012). "Our result demonstrated about 5 and 9 fold Bax/Bcl-2 ratios at the treatment of 1.0 and 2 mg/ml concentration of oxymatrine respectively, compared with controls, which suggested that the alteration of Bax/Bcl-2 expression was associated with oxymatrine-induced pancreatic cancer cells apoptosis." (PMID 21714853, 2011). "Additionally, the regulatory effect of theAkt/mTOR pathway might be associated with Bcl-2/caspase-9/c-myc-mediated apoptosis, resulting in cell proliferation in pancreatic cancer cells." (PMID 30429828, 2018).
pancreatic cancer (continued). "Therefore, altered expression of the Bcl-2 family proteins observed upon honokiol treatment of pancreatic cancer cells in a manner that favors the increase in the ratios of Bax/Bcl-2 and Bax/Bcl-xL could underlie the observed apoptotic effect of honokiol." (PMID 21720559, 2011). "Triptolide and its analogs have been shown to inhibit NF-κB signaling, which in pancreatic cancer cells results in elevated oxidative stress, reduced Bcl-2 expression, and activation of mitochondrial apoptosis pathways." (PMID 40808836, 2025). "A significant mechanism of gemcitabine resistance in pancreatic cancer cells is the paradoxical induction of Bcl-2 overexpression by chemotherapy itself." (PMID 40841912, 2025). "Given the challenges of treating pancreatic cancer, the selective inhibition of Bcl-2 by venetoclax offers a promising avenue to enhance the efficacy of existing chemotherapies while minimizing systemic toxicity." (PMID 40841912, 2025). "Curcumin triggers cell apoptosis in lung, colon, liver, cervical, and pancreatic cancers by up-regulating pro-apoptotic protein expression (Bax and Bad) or by inhibiting anti-apoptotic proteins (Bcl-xL and Bcl-2), as well as activating Caspase pathway." (PMID 40490812, 2025). "For example, in pancreatic cancer models, capsaicin raised intracellular ROS and upregulated Bax while downregulating Bcl-2, culminating in caspase-dependent apoptosis in vitro and in vivo." (PMID 40808836, 2025). "Numerous researches have reported that silibinin can promote the apoptosis by regulating apoptotic-related proteins (e.g., Bax, Bcl-2, and Bcl-xL) and activating Caspases in lung, colon, renal, oral, pancreatic cancers, as well as endometrial carcinoma." (PMID 40490812, 2025). "For instance, pro-apoptotic and anti-proliferative effects of Bcl-2-specific siRNA have been observed in pancreatic cancer cells." (PMID 39680522, 2024). "In a different study, the anticancer potential of CuB was demonstrated in PANC-1 pancreatic cancer cells through the suppression of Bcl-2, survival expression, and STAT3 activation." (PMID 38397437, 2024). "In pancreatic cancer cells, rutin has been shown to promote apoptosis by upregulating miR-877-3p expression, which, in turn, represses bcl-2 transcription." (PMID 39846633, 2024). "For example, exposure to PEITC inhibited the expression levels of Bcl-2 and Bcl-XL, while Bak was increased in human pancreatic cancer cells." (PMID 38473991, 2024). "Anti‐apoptosis proteins such as BCL‐2 are up‐regulated via the activation of the NF‐κB pathway during the emergence of chemoresistance in invasive pancreatic cancer." (PMID 39632551, 2024). "It is important to note that in the present study, RCE induced Beclin-1-independent autophagy and decreased BCl-2 protein levels in pancreatic cancer cells." (PMID 39139643, 2024). "Their findings are consistent with the theory that miR-34 controls the capacity of pancreatic cancer stem cells to self-renew and/or decide their own fate, presumably by directly influencing their targets Bcl-2 and Notch." (PMID 38725047, 2024). "Here, we observed the up-regulation of Claspin and Bcl-2 in pancreatic cancer cell lines when compared with those in normal pancreatic cells." (PMID 38110764, 2023). "It is notable that the elevated abundance of Claspin and Bcl-2 was shown in human pancreatic cancer cell lines (PANC-1, SW1990, AsPC-1, and BxPC-3) when compared to those in normal pancreatic cells (HPDE6C) as measured by Western blotting." (PMID 38110764, 2023).